ORMDL3 (ORMDL sphingolipid biosynthesis regulator 3)
Diseases named in the same sentence as ORMDL3 in open-access papers (continued):
Sharing a sentence is not in itself a finding about the gene and the disease.
asthma (continued). "The first childhood asthma GWAS identified common regulatory variants at and near the ORMDL3/GSDMB/ZPBP2 loci on chromosome 17q21 in three populations of European ancestry, a finding that has now been confirmed in various ethnic groups." (PMID 30086710, 2018). "GSDMA is along with GSDMB and ORMDL3 part of the complex 17q21.1 locus, more research is needed to understand the specific interactions of variants in this region and their role in asthma pathobiology." (PMID 30373671, 2018). "Despite this, the data clearly demonstrate that epithelial ORMDL3 is essential for the generation of AAD and GWAS indicate that only the ORMDL3 isoform is associated with asthma susceptibility." (PMID 27623174, 2017). "This evidence indicated that the difference in ORMDL3 expression levels is directly related to the balance of Th subsets and Th cytokine levels and eventually confers disease susceptibility to asthma and other autoimmune diseases." (PMID 28588209, 2017). "It is worth noting that rs4065275 has been implicated in predisposition to asthma, regulation of ORMDL3 expression levels and TF binding in peripheral blood mononuclear cells and in vitro assays." (PMID 28241063, 2017). "Our findings highlight an important role of huASM-MRC2 (a phylogenetically conserved pattern recognition receptor) that is encoded within chromosome17q23.2 near ORMDL3 17q12-21 of which pathogenic variants increase the risk of asthma." (PMID 28835901, 2017). "Genome-wide association studies have identified the ORM (yeast)-like protein isoform 3 (ORMDL3) gene locus on human chromosome 17q to be a highly significant risk factor for childhood-onset asthma." (PMID 27623174, 2017). "This study demonstrates that ORMDL3, an asthma susceptibility gene identified by genome-wide association studies, contributes to key pathways that promote changes in airway physiology during allergic immune responses." (PMID 27623174, 2017). "Of note, it was recently reported that ORM (yeast)-like protein isoform 3 (ORMDL3) gene is associated with asthma susceptibility, based on the genome-wide association studies." (PMID 28352271, 2017). "Many of the recently identified asthma susceptibility genes, including ORMDL3, are known to be expressed in epithelial cells, and disrupted airway epithelial barrier function is thought to be a critical controller of disease induction." (PMID 27623174, 2017). "GWAS have established a strong correlation between SNPs at the 17q21 locus and the development of asthma and ORMDL3 has been proposed as an asthma susceptibility gene." (PMID 27623174, 2017). "In this study, we attempted to solve this problem by taking a comprehensive approach to predict and test the effects of 17q21 asthma-risk SNPs on expression of ORMDL3 in various cell types." (PMID 27848966, 2016). "When analyzing the impact of ORMDL3-related mutations on these phenotypes in detail, a strong allele specific increase in the risk for persistent wheeze (3-fold) and a diagnosis of asthma (2-fold) was observed." (PMID 27510897, 2016). "Overall, our observations point to several potentially important enhancer elements in the 17q21 locus, especially the ORMDL3 intronic enhancer, whose function is affected by asthma-risk variants." (PMID 27848966, 2016). "The distal IKZF3 intergenic region overlaps ncSNP (rs12946510) and similar to the ORMDL3 intronic enhancer, this region showed increased activity (H3K27ac enrichment) in subjects carrying the asthma-risk allele." (PMID 27848966, 2016). "We show that ORMDL3 expression is most perturbed by the 17q21 asthma-risk SNPs in primary T cell subsets and B cells." (PMID 27848966, 2016). "The three-dimensional (3D) organization of the 17q21 locus in CD4+ T cells was also modified in the asthma-risk alleles to favour recruitment of distal cis-regulatory elements to the ORMDL3 promoter region." (PMID 27848966, 2016).
asthma (continued). "CD4+ T cells showed the greatest increase (threefold) in ORMDL3 expression in individuals carrying the asthma-risk alleles, where ORMDL3 negatively regulated interleukin-2 production." (PMID 27848966, 2016). "The strongest genetic signal for childhood asthma is an association from chromosome 17q21 where the genes ORMDL3 and GSDMA are localized." (PMID 27510897, 2016). "Among asthma susceptibility genes, ORMDL3 and GSDMB, with SNP rs2305480 at chromosome 17q21, are associated with childhood asthma." (PMID 27658857, 2016). "We identified an enhancer region in the first intron of the ORMDL3 gene that overlapped three 17q21 asthma-risk SNPs (rs4065275, rs8076131, and rs12603332), and this region showed increased activity in subjects carrying the asthma-risk allele." (PMID 27848966, 2016). "Polymorphisms at the ORMDL3 locus have been associated with increased risk for asthma, severe asthma, and early viral respiratory infections in asthma." (PMID 26637347, 2015). "In particular, infections with human rhinovirus (HRV), the most common trigger of asthma exacerbations, are associated with a more than 10-fold increased odds ratio for childhood asthma in children who carry the asthma-associated ORMDL3 genotype." (PMID 26637347, 2015). "Given that the asthma-associated ORMDL3 polymorphisms lead to increased expression of ORMDL3, it has been suggested that asthma-associated SNPs negatively regulate SPT resulting in inhibited de novo sphingolipid synthesis." (PMID 26637347, 2015). "ORMDL proteins play an integral role in sphingolipid homeostasis and synthesis, and asthma-associated ORMDL3 polymorphisms have been associated with early viral respiratory infections and increased risk of asthma." (PMID 26637347, 2015). "The ORMDL3 gene, in particular, was associatedwith childhood onset, whereas the HLA-DQ gene was related to later-onset asthma." (PMID 26557257, 2015). "The locus gene orosomucoid 1-like 3 (ORMDL3) that belongs to a gene family encoding ER transmembrane proteins has been recently identified to be related to the pathogenesis of asthma." (PMID 25753687, 2015). "We demonstrated association of ADAM33, IL4 and ORMDL3/GSDMB gene polymorphisms with childhood asthma." (PMID 25768087, 2015). "ORMDL3 on chromosome 17 (17q21) has been strongly and consistently linked to asthma in multiple ethnic groups." (PMID 26637347, 2015). "For example, SNP rs8067378 explained nearly 24% of the variability in expression of ORMDL3 (adjusted p-value < 10-6) in the current study, and has been associated with asthma in several studies." (PMID 25816334, 2015). "Recently, human ORMDL3 was reported as a genetic risk factor associated with asthma in diverse populations." (PMID 25192280, 2014). "The GSDML encodes for gasdermin B protein expressed in epithelial barrier function and skin differentiation, influencing the expression of the neighbouring gene ORMDL3 and thus contributing to asthma susceptibility." (PMID 25299150, 2014). "Moffatt and colleagues first reported that multiple single nucleotide polymorphisms (SNPs) on chromosome 17q21 linked ORMDL3 (orosomucoid 1-like 3) to the risk of developing childhood asthma." (PMID 23369242, 2013). "ORMDL3 was identified as an asthma candidate gene by Genome-wide association studies in diverse human populations." (PMID 24204796, 2013). "One particular gene, ORMDL3, is of interest because of its association with asthma, IBD, and Type I diabetes – all of which are caused by immune-mediated pathology." (PMID 23369242, 2013). "Recently, a GWAS study focusing on childhood asthma has identified a locus on chromosome 17q12-21 (encoding ORMDL3 and GSDMB) as a risk factor for predominantly childhood-onset asthma, but not for atopy, and overall not for adult-onset asthma." (PMID 23936416, 2013).
asthma (continued). "One of the first studies adopting this approach studied lymphoblastoid cell lines, established from a cohort of children with asthma, which found that expression-associated SNPs (eSNPs) modulating ORMDL3 were also the most significant GWAS SNPs for asthma." (PMID 23122694, 2013). "The gene ORMDL3 was shown to be associated with early-onset asthma susceptibility in multiple independent genome-wide and candidate-gene association studies." (PMID 23369242, 2013). "Considerable evidence supports the deduction that ORMDL3 is associated with the development of asthma." (PMID 23577138, 2013). "ORMDL3 is a candidate gene of childhood onset asthma, and high-transcript of ORMDL3 is associated with the development of asthma." (PMID 24204796, 2013). "It is essential to validate the genetic associations linking ORMDL3 with asthma through functional studies that confirm the biological relevance of this gene in disease." (PMID 23369242, 2013). "The exception is exposure to maternal and environmental tobacco smoke that has been reported to increase the strength of association between some novel genes and asthma e.g. the ORMDL3 locus on 17q21 and PCDH1 on 5q31-q33." (PMID 23663440, 2013). "In the original GWAS study, the SNPs associated with asthma in the 17q21 susceptibility locus were also associated with transcript levels of ORMDL3 in lymphoblastoid cell lines, suggesting that ORDML3 was the causal gene." (PMID 23209423, 2012). "Several lines of evidence point to ORMDL3 as the best 17q21 candidate causal gene for childhood asthma." (PMID 22271045, 2012). "They observed associations with asthma, particularly childhood-onset asthma, at multiple loci (ORMDL3/GSDMB, IL1RL1/IL18R1, HLA-DQ, IL33, SMAD3, and IL2RB)." (PMID 23028483, 2012). "A recent study also showed that asthma risk alleles on 17q21 were associated with increased ORMDL3 and GSDMA gene expression and elevated IL-17 secretion in cord blood mononuclear cells." (PMID 23209423, 2012). "Genome-wide association studies of asthma have identified a novel region containing ORMDL3 at chromosome 17q21 that is strongly associated with childhood-onset asthma and significantly linked to ORMDL3 transcript abundance." (PMID 21985515, 2011). "Recent genome-wide association studies (GWAS) for asthma have identified novel genes such as ORMDL3, CHI3L1 and DENND1B, and chromosomal regions such as 9q21.31." (PMID 22188591, 2011). "Examples include the association of IL23R variants with Crohn's disease (CD), psoriasis and ankylosing spondylitis, of PTPN2 variants with CD and type 1 diabetes, and of ORMDL3 variants with asthma and CD." (PMID 21072187, 2010). "Currently, among regions reported to be associated with asthma, the one on chromosome 17q21 near ORMDL3 [MIM 610075] has been the most consistently replicated." (PMID 20698975, 2010). "The first genome wide association study (GWAS) for childhood asthma identified a novel major susceptibility locus on chromosome 17q21 harboring the ORMDL3 gene, but the role of previous asthma candidate genes was not specifically analyzed in this GWAS." (PMID 21103062, 2010). "ORMDL3 is a poorly characterized gene and the underlying mechanism for the association with asthma is unclear." (PMID 18197984, 2008). "Using whole genome association variants in the ORMDL3 gene were shown to be associated with childhood onset asthma." (PMID 18442398, 2008). "However, the impaired generation of sphingolipids due to ORMDL3 overexpression is associated with asthma exacerbation and airway hyperresponsiveness." (PMID 40001485, 2025). "Orosomucoid-like protein 3 (Ormdl3) gene which is associated with asthma have been found to alter sphingolipid levels including CER, and augmented the expression of pyroptotic markers such as NLRP3 and GSDM-D in lung tissues of obese asthmatic mice and human bronchial epithelial cells." (PMID 41335598, 2025). "ORMDL3 polymorphisms are associated with an increased risk of asthma." (PMID 40559469, 2025).
asthma (continued). "ORMDL3 has also been associated with asthma and was shown to regulate mitochondrial calcium influx." (PMID 38267512, 2024). "ORMDL3 polymorphisms in the patients might be the reason for enhanced expression as observed before for the asthma patients." (PMID 38417794, 2024). "Interestingly, the index variant of the current GWAS (rs9303281) was suggested to modulate ORMDL3 expression and asthma risk in rhinovirus-treated airway epithelial cells." (PMID 39299705, 2024). "For subjects with risk alleles, there was increased imprinting of ORMDL3 genes which might contribute to worsening asthma hallmarked by chronic inflammation and airway sensitization." (PMID 40104184, 2024). "Like GSDMB, increased expression of ORMDL3 has been linked to interferon signaling and immune response in the context of asthma, and we suggest that similar regulatory pathways may play a role in susceptibility to severe bronchiolitis." (PMID 39299705, 2024). "Increased ORMDL3 gene expression was detected early in life in cord blood mononuclear cells sampled from donors with asthma-risk SNPs within the 17q12 – q21 locus, suggesting that ORMDL3 may play a role in early immune maturation." (PMID 38715613, 2024). "The asthma risk alleles in ORMDL3 affect the expression of ORMDL3 and have subsequent effects in binding of the protein and interleukin production in blood and nasal epithelial cells, where it was recently shown that sphingolipid levels depend on the ORMDL3 expression levels." (PMID 36967681, 2023). "One of the foremost sphingolipids investigated in the context of asthma is Orosomucoid like 3 (ORMDL3), which encodes an ER-resident transmembrane protein that regulates the activity of serine palmitoyltransferase (SPT), the first and rate-limiting enzyme for sphingolipid biosynthesis in cells." (PMID 36837831, 2023). "Moreover, single‐nucleotide polymorphisms near ORMDL3, which lead to its increased expression, are associated with childhood asthma." (PMID 36350249, 2023). "ORMDL3 and gasdermin B. GWAS suggest that chromosome 17q21 is linked to asthma." (PMID 36078171, 2022). "Interestingly, numerous Ca2+-dependent transcription factors like c-FOS, nuclear factor of activated T cell (NFATC1), and cAMP response element–binding protein (CREB1) as well as the asthma-associated protein ORMDL3 were downregulated in the NCLX KD HASMCs." (PMID 35841929, 2022). "ORMDL3 gene is located in the q2 region of chromosome 17 and is a susceptibility gene for asthma." (PMID 35972600, 2022). "Interestingly, asthma-risk variants identified in several studies have been mapped to 17q12-21 locus, including ORMDL3, GSDML, and CDHR3 genes and have yielded several functional validations." (PMID 35693821, 2022). "SPT function is regulated by ORMDLs, with the human ORMDL3 being linked to asthma." (PMID 36211429, 2022). "The colocalized SNP is in LD (r2 > 0.85 in the 1000 Genomes CEU reference panel) with other previously reported asthma-associated GWAS SNPs in this region, including some that were reported as eQTLs for ORMDL3 and GSDMB, primarily in resting blood immune cells." (PMID 34629083, 2021). "Orosomucoid-like 3 (ORMDL3) gene was first identified in 2007 as an asthma risk gene." (PMID 33679742, 2021). "Evidence now indicates that the association between the 17q21 ORMDL3 locus and childhood-onset asthma is also limited to those children with HRV-induced wheezing in early life, however the mechanism for this interaction remains unclear." (PMID 34001091, 2021). "ORMDL3 may be associated with asthma, AR, and other inflammatory diseases because of its ability to regulate UPR and S1P synthesis." (PMID 34288557, 2021). "All-trans retinoic acid (ATRA) is an active metabolite of vitamin A, which is associated with increased ORMDL3 and shows protective effects on asthma, including maintaining airway epithelial integrity, inhibiting asthma effector cell differentiation, modulating immune response, etc.." (PMID 35126453, 2021).
asthma (continued). "Polymorphisms at ORMDL3 locus have been associated with increased risk for asthma, severe asthma, and early viral respiratory infections, and it is a well-known risk factor for persistent wheezing and a risk factor for asthma development." (PMID 35386967, 2021). "These ORMDL3-induced changes in ASM may contribute to the development of AHR in childhood onset asthma, which is highly linked to ORMDL3 on chromosome 17q12-21." (PMID 33661765, 2021). "In the end, we hypothesize that skewed CD4+ T cell differentiation in the context of elevated ORMDL3 likely culminates in chronic inflammation associated with heightened disease pathogenesis in asthma patients carrying the 17q12–21 risk SNPs." (PMID 33424845, 2020). "In another human study, circulating sphingolipids were inversely associated with childhood asthma and recurrent wheeze, and those with high-risk ORMDL3 expression-promoting genetic variants exhibited limited benefit from vitamin D supplementation in comparison to those with low-risk variants." (PMID 32155960, 2020). "The human ORMDL1 and ORMDL2 genes, residing in other chromosomes than the ORMDL3 gene, might also be associated with asthma, as peripheral blood mononuclear cells from asthmatic patients exhibited increased expression of ORMDL1 and ORMDL2 genes." (PMID 33643282, 2020). "Importantly, functional validation of GWAS candidate asthma risk genes have uncovered key roles in HRV infection susceptibility (ORMDL3 and CDHR3) and TGFβ signalling (GSDMB, TGFBR1, and SMAD3)." (PMID 32887352, 2020). "As ORMDL3 is associated with childhood-onset asthma, ORMDL3’s influence on the inflammatory pathway may be age-dependent; however, no published studies have examined this." (PMID 31992292, 2020). "Since that time, numerous studies have investigated how altered ORMDL3 expression might predispose to asthma and other autoimmune/inflammatory diseases." (PMID 33424845, 2020). "Furthermore, the association of ORMDL3 with asthma was validated in Latinos/Hispanics (min p = 1.90 × 10−15), which have been also extensively associated with asthma across different populations." (PMID 30805318, 2019). "Given that elevated ORMDL3 protein levels are associated with diabetes, ulcerative colitis, Crohn's disease, and asthma, the sequestration of ORM family proteins from the ER and their subsequent ubiquitin‐dependent degradation likely has pathophysiological implications." (PMID 31368600, 2019). "As examples of this, the risk allele for susceptibility variants near ORMDL3 is significantly more common in cases with childhood onset asthma, while the association near CDHR3 might be specific to children with early onset and severe exacerbations." (PMID 29333270, 2017). "It is widely accepted that elevated expression of ORMDL3 confers higher risk for asthma." (PMID 28241063, 2017). "In the Swedish birth-cohort BAMSE, Acevedo and colleagues studied the association of childhood asthma with SNPs, regional DNA methylation, and gene expression at the GSDMB/ORMDL3 locus located at 17q21, a well-studied asthma-susceptibility locus found in ethically diverse populations." (PMID 27777592, 2016). "Thus, the asthma-risk haploblock harbours linked SNPs that switch the binding site of CTCF from the ZPBP2 to the ORMDL3 intronic region." (PMID 27848966, 2016). "Thus, we confirmed that the presence of asthma-risk SNP (rs4065275) introduces a CTCF-binding site in the ORMDL3 intronic region that harbours an active enhancer." (PMID 27848966, 2016). "We noted that the effect of asthma-risk variants on ORMDL3 expression was completely lost when primary naive CD4+ T cells were expanded in culture for a few days, suggesting in vitro expansion per se may dampen the effects of the 17q21 variants." (PMID 27848966, 2016).